ADA (adenosine deaminase)
Diseases named in the same sentence as ADA in open-access papers (continued):
Sharing a sentence is not in itself a finding about the gene and the disease.
autism (3 papers, 2011 to 2022). Persistent deficits in social interaction and communication and interaction as well as a markedly restricted repertoire of activity and interest as well as repetitive patterns of behavior. "A significantly increased frequency of ADA Asp8Asn polymorphism (ADA2 allele) was reported by two independent case-control studies of individuals with autism of Italian descent." (PMID 36339838, 2022). "Together, these findings support a contribution of the decreased activity of ADA reported in the present study to the dysfunction in normal adenosine homeostasis in Saudi patients with autism during prenatal and perinatal brain development." (PMID 22958401, 2012). "We found a significant elevation of creatine, 5'-nucleotidase, GABA, and glutamic acid and a significant decrease in the enzymatic activity of ADA and glutamine level in patients with autism compared with healthy controls." (PMID 22958401, 2012). "The finding of elevated plasma adenosine in 33% of the autism group is consistent with two previous studies and suggests an impairment in adenosine deaminase since adenosine levels are normal." (PMID 21651783, 2011). "Lower ADA activity in patients with autism might also be related to the increased levels of interleukin-6 and tumor necrosis factor-α, and the impaired Ca2+ and K+ homeostasis that were reported from two studies using the same investigated autistic samples." (PMID 22958401, 2012). "Therefore, a possible relationship between the losses of adenosine homeostasis due to the currently reported reduced activity of ADA, and the impairment of neurotransmitter profile is suggested in patients with autism." (PMID 22958401, 2012). "Adenosine was slightly higher (marginally significant) in children with autism, which may indicate that some children have an impairment in adenosine deaminase." (PMID 21651783, 2011). "In the present study, the significant increase in 5'-NT activity in patients with autism compared with control subjects might be related to the significantly lower ADA activity recorded in the same samples, as lower ADA could lead to the accumulation of adenosine and AMP." (PMID 22958401, 2012). "As other studies reported neurological and behavioral problems in patients with ADA deficiency and SCID, but not autism, further studies are warranted in order to dissect the ADA gene role in ASD." (PMID 36339838, 2022).
cardiac arrhythmia (3 papers, 2006 to 2020). Any disturbances of the normal rhythmic beating of the heart or MYOCARDIAL CONTRACTION. "From its first application in adenosine deaminase deficiency, through the years, its application has evolved to vascular angiogenesis and cardiac arrhythmias." (PMID 16943902, 2006).
chronic heart failure (3 papers, 2014 to 2017). "Since endogenous Ado levels are affected by the enzyme Ado deaminase (ADA), polymorphisms within the ADA gene may exert some effect on chronic heart failure (CHF)." (PMID 25170811, 2014). "In chronic heart failure adenosine accumulates, probably as a result of lowered adenosine deaminase (ADA) gene expression and raised CD73 activity." (PMID 28993732, 2017).
chronic lung disease (3 papers, 2010 to 2022). According to the definitions of the American and British Thoracic Societies, including pulmonary functional tests, X-rays, and CT scans for items such as fibrosis, bronchiectasis, bullae, emphysema, nodular or lymphomatous abnormalities. "Investigations using adenosine deaminase (ADA)-deficient mice have also provided compelling evidence that accumulation of adenosine in the lung can lead to the development and exacerbation of chronic lung disease." (PMID 35479074, 2022). "In the current study, we show that the pro-fibrotic mediator IL-6 is produced by alveolar macrophages in the airways of ADA-deficient mice that develop features of chronic lung disease in response to elevations in adenosine." (PMID 21799929, 2011). "CD73 levels are up-regulated in the lungs of mouse models with chronic lung disease including ADA-deficient mice and mice exposed to bleomycin." (PMID 20169073, 2010).
Chronic Lymphocytic Leukemia (3 papers, 2019 to 2021). "Conversely, ADA activity was increased in cancerous tissue from breast, kidney, and colorectal tumours, in serum of patients with bladder ovarian, laryngeal, and head and neck squamous cell carcinomas and in lymphocytes of patients with chronic lymphocytic leukaemia (CLL)." (PMID 31547393, 2019).
combined immunodeficiency syndrome (3 papers, 2011 to 2021). A combined immunodeficiency in which other clinical features are present in other organ systems in addition to immunodeficiency. "We also assayed the growth properties of LCLs derived from patients with genetically confirmed mutations in ADA conferring severe combined immunodeficiency syndrome." (PMID 33497421, 2021). "The first successful therapeutic gene therapy in humans in the early 1990s involved treating two children with severe combined immunodeficiency syndrome (SCID) caused by a genetic defect in the enzyme adenosine deaminase (SCID-ADA)." (PMID 24098300, 2013).
cryptococcal infection (3 papers, 2015 to 2025). "Even in cases with elevated ADA, cryptococcal infection should be considered in patients with unexplained exudative effusions." (PMID 41458507, 2025).
deafness (3 papers, 2016 to 2019). An inherited or acquired condition characterized by the complete loss of the ability to hear from one or both ears. "Although there was no visible relationship between severity of deafness and dATP levels, affected patients also showed no identifiable predisposing factors; therefore, the role of ADA deficiency in auditory abnormalities needs to be investigated and further defined." (PMID 27579027, 2016). "Importantly, these children were transplanted without any conditioning and so the deafness could not be attributed to side effects of treatment, thus implicating metabolic perturbation due to ADA deficiency." (PMID 27579027, 2016). "Elevated concentrations of Ado have been found in the brain of ADA–/– mice, and it is possible that the damage is related to elevated dATP, although a previous study in 12 ADA-SCID patients showed no apparent correlation between dATP at the time of diagnosis and deafness." (PMID 30918508, 2019).
developmental delay (3 papers, 2016 to 2021). "Diverse neurological abnormalities, such as seizures, developmental delay, and cognitive impairment have frequently been reported among ADA-deficient patients." (PMID 30918508, 2019). "Developmental delay and brain abnormalities have frequently been reported in ADA-deficient patients." (PMID 30918508, 2019). "Hearing threshold of these ADA–/– mice (n = 5) at 31–35 days old were still increased at both 8 and 16 kHz (66.3 ± 13.6 and 58.5 ± 18.5 dB, respectively) compared to ADA+/– littermates controls, indicating that the hearing abnormalities were not due to a developmental delay." (PMID 30918508, 2019).
Diamond-Blackfan anemia (3 papers, 2014 to 2024). A congenital aregenerative and often macrocytic anemia with erythroblastopenia. "In this report, we describe a 10-month-old female with Diamond-Blackfan anemia that initially presented with macrocytic anemia with reticulocytopenia and an elevated erythrocyte adenosine deaminase level." (PMID 38988374, 2024).
extrapulmonary tuberculosis (3 papers, 2024 to 2025). A tuberculosis that occurs at body sites other than the lung. "We aimed to assess the plasma levels of ferritin, C-reactive protein (CRP), and adenosine deaminase (ADA) at baseline and their utility as biomarkers to monitor response to treatment in extrapulmonary tuberculosis (EPTB) patients." (PMID 39623309, 2024).
Hearing impairment (3 papers, 2014 to 2023). A decreased magnitude of the sensory perception of sound. "ADA deficiency has also been reported to be associated with sensorineural hearing loss." (PMID 37273692, 2023). "Additionally, ADA-deficient patients suffer from hearing impairment." (PMID 30918508, 2019).
Hydrocephalus (3 papers, 2021 to 2023). Hydrocephalus is an active distension of the ventricular system of the brain resulting from inadequate passage of CSF from its point of production within the cerebral ventricles to its point of absorption into the systemic circulation. "Also, TBM patients typically showed lymphocytic pleocytosis, low glucose levels, elevated proteins, and increased adenosine deaminase (ADA) in the CSF analysis, as well as vasculitis, hydrocephalus, and basal meningeal enhancement in the brain magnetic resonance imaging (MRI)." (PMID 34007850, 2021).
inflammatory bowel disease (3 papers, 2021 to 2022). A spectrum of small and large bowel inflammatory diseases of unknown etiology. "This study aimed to determine the frequency of ADA in patients with inflammatory bowel disease (IBD) during induction and maintenance therapy with biosimilar infliximab (CT-P13) using the ELISA (enzyme-linked immunosorbent assay) method." (PMID 34208676, 2021).
laryngeal carcinoma (3 papers, 2010 to 2023). Carcinoma that arises from the laryngeal epithelium. "The previous publication suggested that ADA activity in the saliva of preoperative patients with oral and laryngeal cancer is significantly lower compared to healthy controls." (PMID 35967411, 2022).
liver cancer (3 papers, 2021 to 2024). An epithelial or non-epithelial malignant neoplasm that arises from the liver. "In liver cancer, elevated ADA is correlated with serum atezolizumab concentrations and impaired functions of CD8-positive T cells, including suppressed secretion of interferon-γ and tumor necrosis factor-α." (PMID 39445019, 2024). "Moreover, among of them, RFC4, ZWINT, UPF3B, NCBP2, ADA, SF3A3 and GTF2H1 are independent prognostic indicators of liver cancer." (PMID 33516217, 2021).
liver fibrosis (3 papers, 2017 to 2024). "We have recently demonstrated that depletion of adenosine deaminase acting on double-stranded RNA (ADAR1) from mouse hepatocytes leads to HSC activation and induction of inflammation and hepatic fibrosis that is mediated by interleukin 6 (IL-6)." (PMID 28472150, 2017). "In addition, we observed significant positive correlations between the liver fibrosis score and ADA and GGT levels, while a significant negative correlation was found with PAB levels." (PMID 38141111, 2024). "In addition, we discovered that the results of some liver tests (including ADA, GGT and PAB levels) were significantly correlated with liver fibrosis, and the levels of some bile acids (including GCDCA, THCA, Total CDCA, and Total BAs) were significantly correlated with liver fibrosis." (PMID 38141111, 2024).
lung adenocarcinoma (3 papers, 2022 to 2025). A carcinoma that arises from the lung and is characterized by the presence of malignant glandular epithelial cells. "The knockdown of ADA inhibited proliferation, migration, and invasion in lung adenocarcinoma cell lines." (PMID 37081889, 2023). "Finally, we further explored the role of ADA (Adenosine deaminase) in the lung adenocarcinoma cell lines through the knockdown of ADA." (PMID 37081889, 2023). "Additionally, the knockdown of ADA dramatically inhibited migration of lung adenocarcinoma and also inhibited its invasive ability." (PMID 37081889, 2023). "Overall, our findings indicated that ADA may promote the proliferation, migration, and invasion of lung adenocarcinoma." (PMID 37081889, 2023).
malaria (3 papers, 2006 to 2022). Malaria is a serious and sometimes fatal disease caused by a parasite that commonly infects a certain type of mosquito which feeds on humans. "A multivariable logistic regression model identified adenosine deaminase (OR = 1.0115, 95% CI: 1.0030–1.0201, p = 0.0080) and parasitemia (OR = 2.0700, 95% CI: 1.2584–3.4050, p = 0.0042) as factors associated with severe malaria." (PMID 36439238, 2022). "Adenosine deaminase and parasitemia were found to be independent risk factors for severe malaria in patients with imported malaria (OR = 1.0088, 95% CI: 1.0010–1.0167, p = 0.0272 and OR = 2.0700, 95% CI: 1.2584–3.4050, p = 0.0042, respectively)." (PMID 36439238, 2022). "In mosquitoes, ADA activities were detected in the saliva of Culex pipiens quinquefasciatus (vector of avian malaria and West Nile virus) and A. aegypti (vector of Dengue and Yellow Fever viruses), but not in the Anopheline mosquito Anopheles gambiae (vector of human malaria)." (PMID 26313460, 2015).
mastitis (3 papers, 2016 to 2023). Inflammation of breast tissue during lactation or postpartum due to an obstructed duct or infection. "We speculate that the domain changes in ADA would alter its function via the AS mechanism, thus leading to different susceptibilities to mastitis." (PMID 27459697, 2016). "In serum, ADA activity is similar in the healthy and ketosis cows, showing the lowest activities meanwhile animals with mastitis, laminitis, or metritis have significantly higher activities." (PMID 36607499, 2023). "Some immune-related genes, such as ITGB6, MYD88, ADA, ACKR1, and TNFRSF1B, and their potential relationships with mastitis were highlighted." (PMID 27459697, 2016). "However, this principle does not apply to our case, as serum ADA activity is statistically the same for CTRL cows as for those with ketosis, it is similar for those with mastitis (MAS group) or metritis (MET group), but different for those with laminitis (LAM group)." (PMID 36607499, 2023).
mesangial sclerosis (3 papers, 2018 to 2021). "Reports of renal involvement in ADA-deficiency include the occurrence of mesangial sclerosis found in 7/8 autopsies of ADA-deficient patients, with 6/8 also demonstrating cortical sclerosis of the adrenal glands." (PMID 29690908, 2018). "Renal abnormalities described with ADA defect (such as diffuse mesangial sclerosis) could result in nephrotic syndrome." (PMID 33628209, 2020).
myocardial ischemia (3 papers, 2020 to 2022). A disorder of cardiac function caused by insufficient blood flow to the muscle tissue of the heart. "It was reported that CAPE exhibited cardioprotective effects in short-term myocardial ischemia in rats through the reduction in xanthine oxidase (XO) and adenosine deaminase (ADA) activities and antioxidant effects." (PMID 34444688, 2021). "Summarizing, ADA could be a promising therapeutic target in myocardial ischemia-reperfusion injury." (PMID 33053898, 2020).
parasitemia (3 papers, 2020 to 2022). "where ADA is blood adenosine deaminase (U/L), Parasitemia is blood parasitemia (/μl), and df is the degrees of freedom." (PMID 36439238, 2022). "The pre-treatment with curcumin in rats infected with T. evansi decreased parasitemia and mortality, maintained the NTPDase activity reduced and enhanced ADA activity on the surface of lymphocytes." (PMID 34858878, 2021). "The serum adenosine deaminase (ADA) activity was therefore assessed as this can potentially influence host suppressive Th2 immune response (IL-10) during the progression of early parasitemia in asymptomatic individuals." (PMID 32555598, 2020).
rheumatic disease (3 papers, 2010 to 2021). "Other causes of increase in ADA activity include bacterial infections, rheumatic disease and lymphoproliferative disorders." (PMID 21629524, 2010). "Synovial ADA fluid measurement, in association with CRP and ESR levels, can distinguish OA from other rheumatic diseases, like RA." (PMID 32984382, 2020). "Synovial fluid ADA measurement, in association with C-reactive protein (CRP) and erythrocyte sedimentation rate (ESR) levels, makes it possible to distinguish OA from other rheumatic diseases, like RA." (PMID 32984382, 2020).
ulcerative colitis (3 papers, 2017 to 2025). An inflammatory bowel disease involving the mucosal surface of the large intestine and rectum. "In some Indian studies, 124 patients with ulcerative colitis and Crohn’s disease received prolonged treatment with Bs-ADA (ExemptiaTM), and nine developed TB." (PMID 36960229, 2023).
vasculitis (3 papers, 2021 to 2023). "However, it should be noted that in our later study, it was rather membrane-anchored ADA1 that marked endothelial cell activation, while changes in soluble ADA were less pronounced in experimental models of vasculitis or in human specimen." (PMID 37685949, 2023).
Acute hepatitis (2 papers, 2023 to 2025). Acute hepatic injury resulting from inflammation typically accompanied by increased serum alanine transaminase activity. "There have been case reports of infants with ADA-SCID presenting with acute hepatitis within weeks of birth." (PMID 37208598, 2023).
allergic disease (2 papers, 2021 to 2022). An immune response that occurs following re-exposure to an innocuous antigen, and that requires the presence of existing antibodies against that antigen. "Relatively high immunogenicity was reported for reference omalizumab in this study compared with that in previous studies in patients with allergic disease, possibly due to the use of a more sensitive and drug‐tolerant ADA assay technology." (PMID 36434739, 2022).
aseptic meningitis (2 papers, 2016 to 2023). Inflammation of the membranes surrounding the brain and spinal cord without a bacterial pathogen. "glial fibrillary acidic protein astrocytopathy should be a differential diagnosis in patients with aseptic meningitis with movement disorders or autonomic symptoms and elevated cerebrospinal fluid adenosine deaminase." (PMID 37867900, 2023).
Ataxia (2 papers, 2016 to 2023). Ataxia refers to impaired coordination of voluntary muscle movement. "Here, we investigated the effect of the treatment with Acetyl-DL-leucine on the walking stability of patients with cerebellar ataxia (10x SAOA, 2x MSA-C, 2x ADA, 1x CACNA-1A mutation, 2x SCA 2, 1x SCA 1)." (PMID 27073690, 2016).
B-cell lymphoma (2 papers, 2023). "We further divided all patients into five pathological subgroups (DLBCL, MALT lymphoma, FL, T-cell lymphoma, and other B-cell lymphoma) to examine the major laboratory indicators and found that the LDH and ADA levels fluctuated significantly in patients with DLBCL." (PMID 37397371, 2023).
bacterial pneumonia (2 papers, 2022). Acute infection of the lung parenchyma caused by bacteria (e.g., Streptococcus pneumoniae, Haemophilus influenzae, Chlamydia pneumoniae, Mycoplasma pneumoniae, and Legionella pneumophila). "Additionally, elevated pleural fluid ADA levels are supported by the findings that serum ADA levels were higher in MP pneumonia cases than in other typical bacterial pneumonia cases." (PMID 35268372, 2022).
central nervous system tuberculosis (2 papers, 2021 to 2022). A well-circumscribed mass composed of tuberculous granulation tissue that may occur in the cerebral hemispheres, cerebellum, brain stem, or perimeningeal spaces. "According to the unified clinical standard of Lancet, 2010 and the guideline for central nervous system tuberculosis of the Chinese Academy of Neurology in 2019, the ADA test was not included in the diagnostic standard, so we did not detect the ADA value in serum and CSF." (PMID 36362480, 2022). "CSF adenosine deaminase levels can be helpful in determining the presence of central nervous system tuberculosis when other systemic signs of disease are lacking." (PMID 33467582, 2021).
cognitive deficits (2 papers, 2018). "This action can be useful in fighting tumors, since ADA inhibition could lead to increased cell death, but at the same time, decrease of ADA activity might increase the risk of neurological dysfunction, including cognitive deficits." (PMID 30441833, 2018).
colorectal adenoma (2 papers, 2014 to 2023). An adenoma that arises from the colon or rectum. "A potential interaction was reported in a case-control study including 1331 cases and 1501 controls from the PLCO cohort for a variant (rs244072 at locus 20q13.12) in the region of adenosine deaminase (ADA) in relation to risk of advanced colorectal adenoma." (PMID 37640106, 2023).